CAMK2A (calcium/calmodulin dependent protein kinase II alpha)
Diseases named in the same sentence as CAMK2A in open-access papers (continued):
Sharing a sentence is not in itself a finding about the gene and the disease.
glioma (10 papers, 2008 to 2025). A benign or malignant brain and spinal cord tumor that arises from glial cells (astrocytes, oligodendrocytes, ependymal cells). "CAMK2A, with low expression, is linked to a favorable prognosis in gliomas, but it also paradoxically correlates with reduced efficacy of immunotherapy." (PMID 41141246, 2025). "Comparing glioblastoma and oligodendroglioma as two histological glioma subgroups on the same exon array platform that we used here, French and colleagues recently identified a total of 11 differentially expressed splice variants, one of which overlapped with our validated genes (CAMK2A)." (PMID 18474104, 2008). "As predicted, glioma patients with lower SERPINI1/CAMK2A expression were less likely to benefit from immune checkpoint therapy than patients with higher SERPINI1/CAMK2A expression." (PMID 37706017, 2023). "SERPINI1 and CAMK2A were found to be the only two overlapping genes in both groups, indicating that these genes are not only highly correlated with the progression of glioma but also act as important molecular markers during glioma anesthesia." (PMID 37706017, 2023). "More importantly, the overexpression of CAMK2A remarkably increased the CAMK2A protein expression and have a remarkably reversed effect on the human glioma cells of miR-3200-3p mimics." (PMID 35287547, 2022). "The gain-of-function studies confirmed that CAMK2A overexpression remarkably suppressed glioma cell proliferation and metastasis induced by miR-3200-3p." (PMID 35287547, 2022). "Next, the effect of CAMK2A and miR-3200-3p on glioma cell migration and invasion was further investigated." (PMID 35287547, 2022). "To investigate the interaction between miR-3200-3p and CAMK2A, we transfected the glioma U251 cell with pcDNA3.1-CAMK2A plasmid to rescue the inhibition of CAMK2A induced by miR-3200-3p mimics." (PMID 35287547, 2022). "Higher expression levels of RAB3A, SYP, CAMK2A, and GABRA1, as well as lower expression levels of TYROBP and VSIG4, in glioma patients were associated with improved OS and DFS." (PMID 36072978, 2022). "Extracted data showed that CaMK2A, 2B and 2G were expressed at “lower” and 2D at comparable levels in gliomas (sub-classified into GBM, oligodendroglioma and astrocytoma) in comparison to the normal subjects." (PMID 28663722, 2017). "In GBM-glioma subtype the order of expression from highest to lowest was as follows: CaMK2G > CaMK2B ≥ CaMK2A > CaMK2D." (PMID 28663722, 2017). "Furthermore, the overexpression of CAMK2A reversed this inhibitory effect of miR-3200-3p on the proteins of Raf/Ras/MEK/ERK signaling in glioma cells." (PMID 35287547, 2022). "Therefore, CAMK2A overexpression can overcome glioma cell metastasis suppression induced by miR-3200-3p." (PMID 35287547, 2022). "In addition, the current research investigated the relation between miR-3200-3p and Ca2+/calmodulin dependent kinase 2a (CAMK2A) and examined their effect on glioma cell progression." (PMID 35287547, 2022). "Additionally, Ca2+/calmodulin dependent kinase 2a (CAMK2A) might be the direct target gene of miR-3200-3p, and CAMK2A overexpression reversed the anticancer roles of miR-3200-3p on glioma cellular function." (PMID 35287547, 2022). "MCOLN2, TRPV4, and ITPR2 were significantly highly expressed in glioma tissues, and the three most significantly down-regulated genes (PRKCG, CAMK2A, and HTR2A) had lower expression in tumor tissues." (PMID 41331166, 2025). "Simultaneously, SERPINI1 and CAMK2A were also significantly related to the prognosis of GBM and lower‐grade glioma patients and acted as potential tumor suppressors." (PMID 37706017, 2023). "We identified six hub genes (RAB3A, TYROBP, SYP, CAMK2A, VSIG4, and GABRA1) that predicted the prognosis of glioma." (PMID 36072978, 2022).
glioma (continued). "After a series of database screening tests, we identified 11 modules during glioma progression, followed by six hub genes (RAB3A, TYROBP, SYP, CAMK2A, VSIG4, and GABRA1) that can predict the prognosis of glioma and were validated in glioma tissues by qRT-PCR." (PMID 36072978, 2022). "Therefore, CAMK2A could be a considered gene of miR-3200-3p in human glioma." (PMID 35287547, 2022). "Six hub genes related to glioma diagnosis and prognosis were identified, including RAB3A, TYROBP, SYP, CAMK2A, VSIG4, and GABRA1." (PMID 36072978, 2022). "Moreover, CAMK2A, a homolog of CAMK2B, has been reported to significantly suppress glioma proliferation and metastasis induced by miR-3200-3p when it is overexpressed." (PMID 41050075, 2025). "Therefore, it could be concluded that RAB3A, TYROBP, SYP, CAMK2A, VSIG4, and GABRA1 may play a critical role in glioma by regulating immune cells." (PMID 36072978, 2022). "We hereby showed that “within gliomas” (not to be confused with comparatively lower levels with respect to normal controls), mere examination of the high transcript levels is not sufficient to connect CaMK2A with tumor progressivity." (PMID 28663722, 2017).
breast carcinoma (7 papers, 2016 to 2020). "It is to be noted that inhibition of phosphorylation of CaMK2A was recommended to be beneficial in breast cancer progression." (PMID 28663722, 2017). "However, bacopa and bacoside A which enhance CaMK2A phosphorylation, are also demonstrated to exert excellent cytotoxic effects on breast cancer cells, in hepatocarcinogenesis etc.." (PMID 28663722, 2017). "We next assessed whether CaMKII expression is associated with breast cancer patient outcome by examining CAMK2A, CAMK2B, CAMK2G and CAMK2D mRNA expression in a publically available 1881-sample breast cancer data set25." (PMID 27605043, 2016).
glioblastoma (7 papers, 2008 to 2024). The most malignant astrocytic tumor (WHO grade IV). "This downregulation of miR-3200-3p reduces CAMK2A expression, enhances cell proliferation and colony formation, and significantly promotes glioblastoma cell migration." (PMID 39006969, 2024). "A prior study showed that B. monnieri plant extract and bacoside A enhance CaMK2A and activate its phosphorylation (pCaMK2A) in glioblastoma cells." (PMID 33273550, 2020). "Immunostaining and single cell based image quantitation of the proportion of CaMK2A phosphorylation in treated vs. untreated cells in glioblastoma cells and normal cells clearly suggested significant increase in phospho-CaMK2A in all glioblastoma cell lines vs. their untreated controls." (PMID 28663722, 2017). "Western blot studies supported the real time data in which both non-phospho CaMK2A and its phosphorylation at T286 was found to be significantly higher in treated vs. untreated glioblastoma cells." (PMID 28663722, 2017). "In addition, we also identified key genes, including MMP9, CD44, CDC42, COL1A1, COL1A2, CAMK2A, and CAMK2B, as potential target genes for diagnosing glioblastoma." (PMID 28191466, 2017). "Results showed that GBM (grade IV) had higher levels of non-phosphorylated CaMK2A vs. the lower grades, suggesting that a regulated “phosphorylation inhibition of CaMK2A” was essential for glioblastoma progression to aggressive and malignant form." (PMID 28663722, 2017). "Therefore, we examined the protein levels (via immunohistochemistry) of non-phospho and T286 phosphorylated CaMK2A in glioblastoma patient tissues array which had samples from different grades (astrocytoma-grade 2, 3–4 and multiforme Grade 4) and normal brain tissues." (PMID 28663722, 2017).
Alzheimer disease (6 papers, 2015 to 2025). A progressive, neurodegenerative disease characterized by loss of function and death of nerve cells in several areas of the brain leading to loss of cognitive function such as memory and language. "There is ample evidence suggesting that calcium/calmodulin-dependent protein kinase II alpha (CaMK2A) may play an important role in the pathophysiology of Alzheimer’s disease (AD)." (PMID 31031618, 2019). "↓ of kinase expression (5 μM): GSK3β, CDK5, DYRK1A, CAMK2A, MAPK1, MAPK12, MAPK14.Modulation of the hGMSC transcriptome, ↓ expression of genes involved in Alzheimer's pathogenesis.↓ expression of GSK3b and p‐GSK303B2, which plays a key role in Alzheimer's disease." (PMID 39653426, 2025).
autism (6 papers, 2018 to 2023). Persistent deficits in social interaction and communication and interaction as well as a markedly restricted repertoire of activity and interest as well as repetitive patterns of behavior. "In comparison with serious phenotypes of loss-of-function models of Camk2a leading to autisms-like behavior and defects of learning and memory, partial deletion of NXN in neurons had subtle effects on mouse behavior, suggesting that it acted as a non-essential modulator of Camk2a." (PMID 34198070, 2021). "High levels of jumping behavior have been reported in Shank2 null, Sh3rf2 haploinsufficient, Camk2a-E183V, and Nlgn2 overexpression mice that model genetic risk factors for ASD and in the C58 inbred strain described as a mouse model of autism." (PMID 35227461, 2022). "It is of note, that a loss-of-function mutation of Camk2a leads to autism like behavior in mice, which was not the case in Nestin-NXN-/- mice, and agrees with the hypothesis that NXN is a modulator but not essential." (PMID 34198070, 2021).
autism spectrum disorder (6 papers, 2018 to 2023). A spectrum of developmental disorders that includes autism, and Asperger syndrome. "Notably, a de novo p.E183V mutation in the CAMK2A catalytic domain was shown to cause autism spectrum disorder." (PMID 29784083, 2018). "We linked heterozygous deletion of TSHZ3/Tshz3 gene to autism spectrum disorder (ASD) and used Camk2a-Cre mice to investigate the postnatal function of Tshz3, which is expressed by CPNs but not MSNs." (PMID 34349780, 2021).
lung adenocarcinoma (5 papers, 2020 to 2025). A carcinoma that arises from the lung and is characterized by the presence of malignant glandular epithelial cells. "Evidence indicates that CAMK2A promotes tumor-initiating capacity in lung adenocarcinoma by enhancing SOX2 expression through EZH2 phosphorylation, highlighting its complex involvement in tumor biology." (PMID 41180485, 2025). "In human lung adenocarcinomas (AD), CAMK2A was aberrantly activated in a proportion of cases and was an independent risk factor predicting shorter survivals." (PMID 32483123, 2020). "In the context of lung adenocarcinoma, CAMK2A has been demonstrated to support tumor-initiating cells by upregulating SOX2 through the phosphorylation of EZH2, indicating a potential mechanism by which it may also affect bladder cancer." (PMID 40893939, 2025). "Calcium/Calmodulin dependent protein kinase II alpha (CAMK2A), a key calcium signaling molecule, phosphorylates EZH2 at T487 with suppression of EZH2 activity to support Tumor initiating cells (TIC) maintenance in lung adenocarcinoma." (PMID 37803297, 2023).
Obesity (5 papers, 2013 to 2024). Accumulation of substantial excess body fat. "The role of uroguanylin in mechanisms underlying obesity was examined using Camk2a-Cre-ERT2-Rosa-STOPloxP/loxP-Guca2b mice in which tamoxifen induces transgenic hormone expression in brain." (PMID 27214655, 2016).
Stroke (5 papers, 2013 to 2024). Sudden impairment of blood flow to a part of the brain due to occlusion or rupture of an artery to the brain. "CYFIP1 plays a crucial role in stroke recovery by enhancing synaptic plasticity and dendritic remodeling through its regulation of CAMK2A expression, with disruptions in CYFIP1 impairing these neuroprotective effects." (PMID 39595569, 2024). "We further aimed to assess the potential role of CKB, CaMK2B, CaMK2D, CaMK2A and CMPK as biomarkers of stroke." (PMID 29784938, 2018). "Notably, CaMK2B, but not CaMK2A neither CaMK2D, appeared as a valuable indicator of stroke patient functional outcome." (PMID 29784938, 2018).
dilated cardiomyopathy (3 papers, 2020 to 2025). Cardiomyopathy which is characterized by dilation and contractile dysfunction of the left and right ventricles. "The phosphorylation of calcium/calmodulin-dependent protein kinase II (CAMK2A) increases the opening probability of L-type calcium channels in the sarcolemma and contributes to the development of dilated cardiomyopathy." (PMID 40429682, 2025). "Among the DEGs involved in the dilated cardiomyopathy pathway, the expression levels of ANP, Calm1/2/3, Camk2a/d and Pde2/3/5a were decreased in the GCN2iB group." (PMID 35883870, 2022).
lung carcinoma (3 papers, 2020 to 2023). "Together, results implicated elevated levels of CAMK2A increased lung cancer cell resistance to both target therapy and cisplatin chemotherapy." (PMID 32483123, 2020). "This study unveils the role of calcium/calmodulin‐‐depdendent protein kinase 2 isoform A (CaMK2A)/nuclear factor erythroid 2‐related factor (NRF2)/glutathione S‐transferase pi (GSTP1) axis under hypoxia in lung cancer stem cell maintenance." (PMID 36709476, 2023). "This study provided phenotypic and mechanistic evidence for the TIC supportive role of CAMK2A, implicating a novel predictive and therapeutic target for lung cancer." (PMID 32483123, 2020). "Together, the data showed chronic drug treatment activated CAMK2A in lung cancer cells leading to increased resistance to both EGFR target therapy and cisplatin chemotherapy." (PMID 32483123, 2020). "While microarray data quoted in this study showed a more consistent survival significance of CAMK2A than CAMK2G in lung cancer, more studies would help to clarify their respective roles." (PMID 32483123, 2020). "However, the expressions of pCaMK2A and GSTP1 were positively correlated in both clinical lung cancer samples and lung cancer cell lines, indicating CaMK2A/NRF2 S558 could regulate GSTP1 in a KEAP‐independent manner." (PMID 36709476, 2023). "We also studied the correlation between CaMK2A/NRF2 expression and GSTP1 expression in a lung cancer cell line panel." (PMID 36709476, 2023). "In summary, we showed hypoxia‐induced CaMK2A activation leads to GSTP1 upregulation through direct NRF2 phosphorylation at S558, in turn eliminating ROS and facilitating homeostatic equilibrium through negative feedback, eventually contributing to lung cancer CSC maintenance." (PMID 36709476, 2023).
Parkinson disease (3 papers, 2013 to 2025). A progressive degenerative disorder of the central nervous system characterized by loss of dopamine producing neurons in the substantia nigra and the presence of Lewy bodies in the substantia nigra and locus coeruleus. "Downregulated genes related to Parkinson’s disease and retrograde endocannabinoid signaling, such as Camk2a, also have a role in phosphorylation, oxidoreductase, and ion channel activities." (PMID 40244122, 2025).
tauopathy (3 papers, 2021 to 2024). Neurodegenerative disorders involving deposition of abnormal tau protein isoforms (tau proteins) in neurons and glial cells in the brain. "This is consistent with the recent report of human-like tauopathy in a different Tg rat model expressing the hTau 2N4R isoform under the forebrain-restricted Camk2A promoter." (PMID 39160375, 2024). "For example, neurons in locus coeruleus, the source of noradrenergic input to cortex, appear to express Camk2a, which is the promoter for mutant Tau in this tauopathy model." (PMID 36274955, 2022).
Angelman syndrome (2 papers, 2019 to 2022). A neurogenetic disorder characterized by severe intellectual deficit and distinct facial dysmorphic features. "Finally, we highlight three remarkable cases, each representing the oldest individual ever published with their genetic diagnosis, i. e., Angelman syndrome, Miller–Dieker syndrome, and CAMK2A-related disorder, and describe lessons learned from each of these adults." (PMID 38835877, 2022).
Arrhythmia (2 papers, 2021 to 2023). Any cardiac rhythm other than the normal sinus rhythm. "Inhibition of CAMK2A was shown to reduce occurrence of cardiac arrhythmias for in vivo and ex vivo Chagas disease models." (PMID 36936778, 2023).
Ataxia (2 papers, 2022). Ataxia refers to impaired coordination of voluntary muscle movement. "Cerebellar Camk2a neuronal proteins enriched in mRNA processing and splicing proteins were linked to ataxias, primary lateral sclerosis, and psychiatric disorders, suggesting that splicing dysregulation in cerebellar Purkinje neurons may underlie pathogenesis of these conditions." (PMID 35614064, 2022). "The cerebellar Camk2a proteomic signature was indicative of increased MAPK signaling and mRNA processing (splicing, snRNP assembly) as well as genes related to ataxia, spinal cord disease, and hereditary eye diseases (e.g., retinitis pigmentosa)." (PMID 35614064, 2022).
bipolar disorder (2 papers, 2013 to 2019). A disorder of the brain that causes unusual shifts in mood, energy, activity levels and the ability to carry out day-to-day tasks. "CAMK2A is one gene suggested to be a candidate for bipolar disorder, and decreased CAMK2A mRNA has been found in the prefrontal cortex of patients with the disorder." (PMID 31822292, 2019). "Camk2a+/− mice also harbor brain endophenotypes relevant to bipolar disorder, such as neuronal hyperexcitability and immaturity in the hippocampus and decreased brain pH." (PMID 31822292, 2019).
dementia (2 papers, 2023 to 2025). Loss of intellectual abilities interfering with an individual's social and occupational functions. "Our study revealed that antibodies against CAMK2A were downregulated in patients with dementia and MCI." (PMID 38107644, 2023). "Five autoantibodies (CAMK2A, CKS1B, ETS2, MAP4, and NUDT2) were dysregulated in both dementia and MCI." (PMID 38107644, 2023). "Five autoantibodies in particular, were dysregulated in dementia and MCI, including CAMK2A, CKS1B, ETS2, MAP4, and NUDT2." (PMID 38107644, 2023). "Five autoantibodies were commonly dysregulated in both dementia and MCI, including anti-CAMK2A, CKS1B, ETS2, MAP4, and NUDT2." (PMID 38107644, 2023).
Huntington disease (2 papers, 2016 to 2022). Huntington disease (HD) is a rare neurodegenerative disorder of the central nervous system characterized by unwanted choreatic movements, behavioral and psychiatric disturbances and dementia. "For some of these, we were able to predict the effect of a differential phosphorylation on their activity: the decreased phosphorylation in Huntington’s disease mice of CAMK2A and CAMKK2 allows for calcium/calmodulin binding." (PMID 36523271, 2022).
intellectual disability syndrome (2 papers, 2018 to 2023). "Biallelic variants in CAMK2A have also been recently associated with a similar but more severe intellectual disability syndrome known as intellectual developmental disorder autosomal recessive 63 (OMIM#618095)." (PMID 37510258, 2023).
preeclampsia (2 papers, 2017 to 2025). Preeclampsia is a hypertensive disorder of pregnancy that is characterized by new-onset hypertension with proteinuria presenting after 20 weeks of gestation, and depending on mild or severe forms may initially present with severe headache, visual disturbances, and hyperreflexia. "Cardiac gene expression of Vcam, Edn1, Ccr2, Ctgf, Tgfb1, Tgfb2, Tgfb3, Bnp, Cybb, Mmp2, Mmp9, Timp1, Camk2a, Slc9a1, Nr3c2, and Nr3c1 was not different between mice who had a normal pregnancy and mice who had a preeclampsia-like pregnancy at 5 or 10 weeks postpartum (respectively)." (PMID 40425613, 2025).
triple-negative breast carcinoma (2 papers, 2016 to 2022). An invasive breast carcinoma which is negative for expression of estrogen receptor (ER), progesterone receptor (PR), and human epidermal growth factor receptor 2 (HER2). "We also found that increased CAMK2A mRNA expression was associated with significantly worse distant metastasis free survival in Luminal A and triple negative breast cancer patients." (PMID 27605043, 2016).
alcohol addiction (1 paper, 2021). "It is of note, that Camk2a mutations in mouse addiction models impair dopamine and serotonin mediated reward signaling and lead to earlier transition to severe cocaine use or alcohol addiction." (PMID 34198070, 2021).